RBM42 (RNA binding motif protein 42)
Description:
Binds (via the RRM domain) to the 3'-untranslated region (UTR) of CDKN1A mRNA.
Synonyms: MGC10433
Tractability: Small molecule: a structure with a bound ligand is known. PROTAC: ubiquitination databases record sites on it; its protein half-life has been measured.
Gene: Protein-coding gene on chromosome 19 (35,628,989 to 35,638,927, forward strand). Ensembl gene ENSG00000126254.
Subcellular location: Nucleus; Cytoplasm
Subcellular location (Human Protein Atlas): Nucleoplasm; Cytosol
Pathways (Reactome):
Metabolism of RNA: mRNA Splicing - Major Pathway
Gene Ontology:
Molecular function: protein binding; RNA binding; mRNA binding; nucleic acid binding
Biological process: mRNA splicing, via spliceosome; spliceosomal snRNP assembly
Cellular component: precatalytic spliceosome; spliceosomal complex; U4/U6 x U5 tri-snRNP complex; nucleoplasm; nucleus; cytoplasm
Genetic constraint (gnomAD): Loss-of-function variants: 20 observed, 35.64 expected, observed/expected ratio (o/e) 0.56, 90% interval 0.39 to 0.81. The upper end of that interval is the gene's LOEUF score, 0.81, which puts it in group 3 of 6, group 1 being the genes least tolerant of losing a copy. Missense variants: 510 observed, 588.11 expected, observed/expected ratio (o/e) 0.87, 90% interval 0.81 to 0.93. Synonymous variants: 250 observed, 225.35 expected, observed/expected ratio (o/e) 1.11, 90% interval 1 to 1.23.
Homologues: Orthologues: chimpanzee RBM42 (100% identical), macaque RBM42 (99% identical), dog RBM42 (98% identical), guinea pig RBM42 (98% identical), pig RBM42 (97% identical), rabbit RBM42 (97% identical), rat Rbm42 (97% identical), mouse Rbm42 (97% identical).
Diseases named in the same sentence as RBM42 in open-access papers:
RBM42 is named in the same sentence as 7 diseases in open-access papers, as found by Europe PMC text mining. Sharing a sentence is not in itself a finding about the gene and the disease. The quoted sentences say what the papers report.
asthma (1 paper, 2020). "They include RBM42, STX5, and TRIM41 in asthma, CYP27A1, GM2A, LGALS9, SPI1, and NLRC4 in COPD, as well as ATF3, PPP1R15A, ZFP36, SOCS3, NAMPT, and GADD45B in IPF." (PMID 31952466, 2020). "According to the results, RBM42, STX5, and TRIM41 may have critical functions in asthma." (PMID 31952466, 2020). "These genes included RBM42, STX5, and TRIM41 in asthma, CYP27A1, GM2A, LGALS9, SPI1, and NLRC4 in COPD, ATF3, PPP1R15A, ZFP36, SOCS3, NAMPT, and GADD45B in IPF, LRRC48 and CETN2 in asthma-COPD, COL15A1, GIMAP6, and JAM2 in asthma-IPF and LMO7, TSPAN13, LAMA3, and ANXA3 in COPD-IPF." (PMID 31952466, 2020).
Au-Kline syndrome (1 paper, 2024). "It has been reported that RBM42 interacts with hnRNP K, which is the causative gene for Au-Kline syndrome (AKS)." (PMID 37294900, 2024). "Additionally, p.A438T disrupts the interaction of RBM42 with hnRNP K, which is the causative gene for Au-Kline syndrome with overlapping disease characteristics seen in the index patient." (PMID 37294900, 2024).
lymphoma (1 paper, 2024). A malignant (clonal) proliferation of B- lymphocytes or T- lymphocytes which involves the lymph nodes, bone marrow and/or extranodal sites. "One of these near-universal CRMGs contains a rarely studied RBP, RBM42, that interacts with hnRNP K, is a component of stress granules, and is MYC-sensitive in lymphoma cells." (PMID 39464061, 2024).
cancer (2 papers, 2024 to 2025). A tumor composed of atypical neoplastic, often pleomorphic cells that invade other tissues. "Compound sensitivity across cancer cell lines correlates with dependency on the RBP RBM42, which has been shown to bind to the MYC 5′ UTR and enhance its translation." (PMID 40943063, 2025). "Our findings establish a novel therapeutic modality targeting translational control via mRNA relocalization, with enhanced efficacy against cancer cell lines exhibiting high dependency on an RNA-binding protein which regulates MYC mRNA translation, RBM42." (PMID 40943063, 2025).
neurodevelopmental disorder (1 paper, 2024). A behavioral and cognitive disorder with onset during the developmental period that involves impaired or aberrant development of intellectual, motor, or social functions. "Here, we report a previously unrecognized syndromic neurodevelopmental disorder associated with biallelic loss-of-function variants in the RBM42 gene." (PMID 37294900, 2024).
RBM42 also shares sentences with these, for which no sentence is quoted: lung fibrosis (1 paper); Thrombocytopenia (1).